GPM6B (glycoprotein M6B)
Description:
May be involved in neural development. Involved in regulation of osteoblast function and bone formation. Involved in matrix vesicle release by osteoblasts; this function seems to involve maintenance of the actin cytoskeleton. May be involved in cellular trafficking of SERT and thereby in regulation of serotonin uptake.
Synonyms: M6b; MGC17150; MGC54284
Tractability: Antibody: UniProt places it where antibodies can reach, with medium confidence; UniProt predicts a signal peptide or a membrane-spanning region; its Gene Ontology location is reachable by antibodies, with medium confidence. PROTAC: ubiquitination databases record sites on it; its protein half-life has been measured.
Gene: Protein-coding gene on chromosome X (13,770,939 to 13,938,638, reverse strand). Ensembl gene ENSG00000046653.
Subcellular location: Cell membrane
Gene Ontology:
Molecular function: structural constituent of myelin sheath
Biological process: extracellular matrix assembly; positive regulation of bone mineralization; regulation of actin cytoskeleton organization; regulation of focal adhesion assembly; axon development; central nervous system myelination; negative regulation of protein localization to cell surface; negative regulation of serotonin uptake; nervous system development
Cellular component: membrane raft; myelin sheath; plasma membrane; membrane
Homologues: Orthologues: macaque GPM6B (100% identical), mouse Gpm6b (98% identical), rat Gpm6b (98% identical), chimpanzee GPM6B (87% identical), guinea pig GPM6B (86% identical), dog GPM6B (85% identical), tropical clawed frog gpm6b (74% identical), zebrafish gpm6bb (66% identical), Drosophila melanogaster M6 (24% identical), Caenorhabditis elegans nmgp-1 (15% identical). Paralogues in human: GPM6A (47% identical), PLP1 (39% identical).
Diseases named in the same sentence as GPM6B in open-access papers:
GPM6B is named in the same sentence as 32 diseases in open-access papers, as found by Europe PMC text mining. Sharing a sentence is not in itself a finding about the gene and the disease. The quoted sentences say what the papers report.
breast carcinoma (6 papers, 2013 to 2025). "In breast cancer and bladder cancer, patients with high GPM6B expression usually have a better prognosis." (PMID 41450963, 2025). "Simultaneously, the differentially expressed genes related to breast cancer, such as FHL1, GPM6B, RELN, and CXCL10 were discovered between the two risk groups." (PMID 38748500, 2024). "GPM6B has been proved and can be used as a biomarker for gynecological malignancies and breast carcinoma." (PMID 33294057, 2020). "Some oncology research data have also indicated that GPM6B can be used as a biomarker for gynecological malignancies and breast carcinoma." (PMID 33294057, 2020). "We compared expression of genes related to apoptosis (DR6 and Gpm6B) in the blood of patients suffering from stage I of breast cancer in different grades (I–IV), with healthy controls." (PMID 24696529, 2014). "We found significant changes of mRNA expression levels in tumour vascular genes DR6 and Gpm6B obtained from peripheral blood of patients suffering from different grades of breast carcinoma." (PMID 24696529, 2014). "Interestingly, eight genes (ID4, LTBP4, GPM6B, RGMA, EFCAB1, ALX4, OSR1 and PPARA) were confirmed to be down-expressed in breast cancer tissues, and associated with the overall survival time of breast cancer patients, as high expression of these genes correlate with an improved prognosis." (PMID 32650755, 2020). "The potential target genes of miR-1908-3p in breast cancer included ID4, LTBP4, GPM6B, RGMA, EFCAB1, ALX4, OSR1 and PPARA." (PMID 32650755, 2020). "Based on these findings, a potential miR-1908-3p-mRNA regulatory network, miR-1908-3P-ID4/ LTBP4/ GPM6B/ RGMA/ EFCAB1/ ALX4/ OSR1/ PPARA, contributing to breast cancer onset and progression could be established." (PMID 32650755, 2020).
bladder cancer (3 papers, 2013 to 2025). "Thus, we predicted that lncRNA OCIAD1-AS1 might interact with miR-141-3p/miR-200a-3p to regulate GPM6B/AKAP11 to participate in mechanisms in bladder cancer." (PMID 36003338, 2022). "We found that GPM6B and AKAP11 showed low expression levels in bladder cancer tissue compared to the normal group, supported by RT-qPCR." (PMID 36003338, 2022). "We finally found that GPM6B and AKAP11 were down-regulated bladder cancer tissues compared to normal tissues using the GEPIA database, which was consistent with the results of RT-qPCR." (PMID 36003338, 2022).
glioma (3 papers, 2024 to 2025). A benign or malignant brain and spinal cord tumor that arises from glial cells (astrocytes, oligodendrocytes, ependymal cells). "This indicates that GPM6B expression is associated with the malignant phenotype and prognosis of glioma." (PMID 41450963, 2025). "Moreover, the expression of GPM6B was decreased in higher-grade glioma cells, and patients with lower expression levels of this gene showed an increased risk of glioma development." (PMID 38273037, 2024). "Previous studies indicate that GPM6B expression correlates with glioma grade and neuronal differentiation." (PMID 41450963, 2025). "The relationship between the expression of GPM6B and glioma was analyzed using the CGGA and TCGA databases." (PMID 41450963, 2025). "The finding indicates that GPM6B is primarily subjected to proteasomal degradation in glioma stem cells." (PMID 41450963, 2025). "Further detection in clinical glioma samples confirmed that GPM6B expression is lower in high-grade glioma." (PMID 41450963, 2025). "Overexpression of β-catenin or SOCS3 promoted glioma stem cell growth, whereas GPM6B overexpression in the context of upregulation of β-catenin or SOCS3 markedly attenuated the promoting effect of β-catenin or SOCS3." (PMID 41450963, 2025). "Results showed that GPM6B overexpression suppressed the intracranial growth of glioma stem cells in mice." (PMID 41450963, 2025). "In this study, we found that the expression level of GPM6B decreased significantly with the increase in grade of glioma in both the CGGA and TCGA databases." (PMID 41450963, 2025). "To verify the role of the GPM6B in vivo, we employed an intracranial glioma nude mouse model to investigate its effects on glioma development." (PMID 41450963, 2025). "Our study indicates that GPM6B suppresses the proliferation and stemness maintenance of glioma through the Integrin β1–β-catenin signaling pathway, although the detailed mechanism of GPM6B interaction with Integrin β1 requires further investigation." (PMID 41450963, 2025). "Overexpression of GPM6B suppressed tumor sphere formation and reduced the sphere formation efficiency of glioma stem cells." (PMID 41450963, 2025). "Analysis of the Chinese Glioma Genome Atlas (CGGA) data revealed that the expression level of GPM6B in gliomas decreased with the increase in grade of glioma." (PMID 41450963, 2025). "We performed immunoprecipitation of proteins from glioma stem cells which are followed by mass spectrometry analysis to identify proteins interacting with GPM6B." (PMID 41450963, 2025). "We also found a significant correlation between GPM6B expression and the prognosis of glioma patients, because patients who exhibit high GPM6B expression showing markedly longer overall survival than those with low expression." (PMID 41450963, 2025). "Collectively, these results identify GPM6B as a critical regulator of glioma stemness and a potential therapeutic target for glioma, providing new insights into glioma biology and offering a foundation for future translational research." (PMID 41450963, 2025). "We examined the role of GPM6B in glioma stem cells and found that GPM6B suppressed the sphere-forming capacity of GSCs, accompanied by reduced expression of Wnt pathway–related proteins, including β-catenin, p-STAT3, and c-Myc." (PMID 41450963, 2025). "Interestingly, knockdown of Integrin β1 did not alter the mRNA level of GPM6B but led to an increase in its protein level, which suggested that Integrin β1 regulates the stability of GPM6B protein at the post-transcriptional level in glioma stem cells." (PMID 41450963, 2025). "The expression of GPM6B was negatively correlated with glioma grade and prognosis." (PMID 41450963, 2025). "The expression of GPM6B was negatively correlated with the grade and prognosis of glioma." (PMID 41450963, 2025).
glioma (continued). "GPM6B promoted the transformation of glioma stem cells and inhibited growth of glioma by suppressing Integrin β1–mediated regulation of β-catenin, while reducing its own degradation through inhibition of the ubiquitinase SOCS3, thereby stabilizing its function in glioma." (PMID 41450963, 2025). "In a summary, our findings first demonstrated that GPM6B not only suppresses glioma stem cell capacity and glioma growth by inhibiting Integrin β1–mediated regulation of β-catenin, but also reduces its own degradation by repressing SOCS3-mediated ubiquitination, thereby stabilizing itself in glioma." (PMID 41450963, 2025). "With further investigation, GPM6B may emerge as an important molecular target for neurological disorders and cancer therapy; however, its precise mechanism of glioma remains unclear." (PMID 41450963, 2025). "In clinical specimens, we further observed that GPM6B expression correlated with glioma grade." (PMID 41450963, 2025). "In this study, we aim to elucidate the regulatory role of GPM6B in glioma." (PMID 41450963, 2025). "Finally, the role of GPM6B in glioma progression was validated in nude mouse models." (PMID 41450963, 2025). "Thus, our future studies will focus on determining whether GPM6B mediates glioma stem cell transformation via the WNT signaling pathway." (PMID 41450963, 2025). "Therefore, it is plausible that GPM6B-mediated inhibition of β-catenin signaling may converge with autophagy/apoptosis regulatory networks, further affecting glioma stemness and tumor progression." (PMID 41450963, 2025). "Therefore, we further focus on the role of GPM6B in glioma stem cells." (PMID 41450963, 2025). "Therefore, it is necessary to investigate the role of GPM6B in glioma." (PMID 41450963, 2025). "However, the precise mechanisms of GPM6B in glioma remain unknown." (PMID 41450963, 2025). "Finally, in an intracranial glioma model in nude mice, we observed that GPM6B overexpression suppressed intracranial glioma growth, and GPM6B significantly inhibit the functions of β-catenin and SOCS3 in promoting glioma development in vivo." (PMID 41450963, 2025). "GPM6B may promote the transformation of glioma stem cells and inhibit growth of glioma by suppressing Integrin β1–mediated regulation of β-catenin, while simultaneously reducing its own degradation through inhibition of the ubiquitinase SOCS3, thereby stabilizing its function in glioma." (PMID 41450963, 2025).
melanoma (2 papers, 2013 to 2025). A malignant, usually aggressive tumor composed of atypical, neoplastic melanocytes. "Specifically within tumor samples, we observed an abundant cell type that expressed markers commonly seen in melanoma, including the markers Plp1, Gpm6b, Postn, Mcam, S100b35." (PMID 40571713, 2025).
prostate carcinoma (2 papers, 2020 to 2022). A carcinoma that arises from epithelial cells of the prostate gland. "We will further explore the mechanism of GPM6B's role in prostate cancer in follow-up research and expand the sample size." (PMID 33294057, 2020). "We explored differentially expressed genes in prostate cancer by analyzing TCGA data and found GPM6B downregulated in PCa tissues compared to that in normal prostate tissues." (PMID 33294057, 2020). "The overexpression of GPM6B in prostate cancer cells could inhibit cell proliferation." (PMID 33294057, 2020). "First, the reasons for the differential expression of GPM6B in prostate cancer tissues and normal tissues adjacent to the cancer were not investigated." (PMID 33294057, 2020).
depression (1 paper, 2023). "Hence, the Ile185Met mutation of GPM6B might be associated with major depressive disorder through interactions with SLC6A4." (PMID 37511534, 2023). "GPM6B was significantly down-regulated in the depression suicide completers compared to normal subjects." (PMID 37511534, 2023). "Another study also discovered the reduced expression of GPM6B in the hippocampus of depression suicides, providing further support for the involvement of GPM6B in the pathogenesis of major depression." (PMID 37511534, 2023). "Instead, we saw three rare variants that might be relevant to major depressive disorder, including p.Ala4551Gly of FAT1, p.Val231Leu of HOMER3, and p.Ile185Met of GPM6B." (PMID 37511534, 2023). "In family 2, with two affected sisters diagnosed with major depressive disorder, we detected three rare variants shared by the two sisters in three genes implicated in affective disorders, including p.Ala4551Gly of FAT1, p.Val231Leu of HOMER3, and p.Ile185Met of GPM6B." (PMID 37511534, 2023).
glioblastoma (1 paper, 2023). The most malignant astrocytic tumor (WHO grade IV). "Further, survival predictors based on gene signatures for glioblastoma obtained from microarray experiments achieved 100% accuracy if composed of Gfap, Pzprz1, Gpm6b and Prelp transcripts suggesting that PRELP is involved in extracellular matrix (ECM) remodeling in glioblastoma." (PMID 36818562, 2023).
lung adenocarcinoma (1 paper, 2025). A carcinoma that arises from the lung and is characterized by the presence of malignant glandular epithelial cells. "In addition, a recent study revealed that GPM6B can inhibit the progression of lung adenocarcinoma." (PMID 41450963, 2025).
lymph node metastasis (1 paper, 2020). "In univariate analysis, GPM6B expression, clinical stage, Gleason score, T classification, lymph node metastasis, and distant metastasis were significantly related to OS." (PMID 33294057, 2020). "The GPM6B expression in PCa patient's tumor tissues was significantly related to clinical stage, T classification, lymph node metastasis, and distant metastasis, but not significantly related to age and Gleason score." (PMID 33294057, 2020).
Miscarriage (1 paper, 2015). A pregnancy that ends at a stage in which the fetus is incapable of surviving on its own, defined as the spontaneous loss of a fetus before the 22th week of pregnancy. "The remaining genes assayed had either very low or no expression in cultured chorionic villi from controls (PARK, LIPC, CTNNA3, EGFL6, GPM6B, RAB9A, POU6F2 and C7orf10) and were not assessed in miscarriages." (PMID 25674159, 2015).
mood disorder (1 paper, 2022). A cognitive disorder a disturbance in which the person's mood is hypothesized to be the main underlying feature. "It has been suggested that GPM6B could play a role in regulating SERT cellular trafficking and activity, which could potentially have a broad impact on mood disorders." (PMID 36077051, 2022).
neuronal ceroid lipofuscinosis (1 paper, 2020). "The GPM6B gene encodes a membrane trafficking protein related to brain development, and its dysfunction could possibly be linked to neuronal ceroid lipofuscinosis and Rett syndrome." (PMID 33447134, 2020).
tumor (11 papers, 2012 to 2025). "Previous studies have reported that GPM6B regulates 5-hydroxytryptamine (5-HT) uptake and reduces 5-HT absorption in prostate cancer cells, thereby inhibiting tumor cell proliferation." (PMID 41450963, 2025). "In tumor sphere formation assay, the diameter of spheres in the GPM6B overexpression group was smaller than that in the control group, and the expression of β-catenin, p-STAT3, and c-Myc also reduced." (PMID 41450963, 2025). "As a transmembrane protein, GPM6B participates in multiple physiological and pathological processes, and is particularly relevant to the nervous system and tumor biology." (PMID 41450963, 2025). "According to the IHC scores of the tumor tissues, the study cohort was divided into two groups; 49 patients made up the low GPM6B expression group (IRS < 4), and 45 patients made up the high GPM6B expression group (IRS ≥ 4)." (PMID 33294057, 2020). "The paper describes the expression of Dr6 and Gpm6B as members of apoptotic machinery in correlation with intensity of neovascularization during tumour growth and metastatic processes." (PMID 24696529, 2014). "The overexpression of DR6 and Gpm6B leads to abnormal signalling pathways that contribute to the regulation of apoptotic processes in EC and tumour cells." (PMID 24696529, 2014). "In our study, it was the case for patient 5 who was identified based on HRM as a cancer subject only when GPM6B methylation in the tumor sample was compared with NorAdjRef." (PMID 23950870, 2013). "Furthermore, we found that GPM6B can inhibit tumor proliferation through the Wnt/β-catenin signaling pathway." (PMID 41450963, 2025). "In conclusion, we identified GPM6B as a tumor suppressor in PCa." (PMID 33294057, 2020). "Indeed, methylation of GPM6B probe in the tumor sample from patient 5 was the same as in its adjacent normal tissue, however it was different from NorAdjRef confirming the use of an averaged normal as a standard for comparison." (PMID 23950870, 2013). "Temperature values of melting curve peaks of GPM6B (A), MAGEA12 (B) and FCRL1 (C) amplicons in tumor samples and normal liver tissues in Chinese (Ch) and Bangladeshi (B) cohorts as analyzed by HRM." (PMID 23950870, 2013). "To assess the level of TVM expression (DR6 and Gpm6B) and explore its potential pro- and antiapoptotic role during tumour development, we examined the expression of DR6 and Gpm6B mRNAs by RT-PCR and Western blot analysis isolated from human peripheral whole blood." (PMID 24696529, 2014). "The study also refers to increase of tumour vascular proteins levels coded by DR6 and Gpm6B genes." (PMID 24696529, 2014).
cancer (3 papers, 2013 to 2022). A tumor composed of atypical neoplastic, often pleomorphic cells that invade other tissues. "A probe within MAGEA12 should be used in combination with GPM6B in order to detect cancer as melting curves for tumors of a few patients with PVTT overlap with NorAdjRef curve." (PMID 23950870, 2013). "In other words, miR-141-3p and miR-200a-3p were highly-expressed, but GPM6B and AKAP11 were low-expressed in cancer tissues." (PMID 36003338, 2022). "The probes correspond to three genes GPM6B, MAGEA12, and FCRL1 that were overexpressed and demethylated in our set of HCC patients and up-regulated in many other types of cancer." (PMID 23950870, 2013). "MAGEA12 was shown before to be repressed in normal cells by promoter methylation and activated in cancer cells by demethylation, whereas the role of GPM6B and FCRL1 methylation in promoter activity was not previously tested." (PMID 23950870, 2013).
psychiatric disorder (1 paper, 2025). A disorder characterized by behavioral and/or psychological abnormalities, often accompanied by physical symptoms. "In addition, genetic variations in GPM6B have been linked to altered phenotypes in certain psychiatric disorders." (PMID 41450963, 2025). "Aberrant expression of GPM6B may be associated with certain psychiatric disorders." (PMID 41450963, 2025).
GPM6B also shares sentences with these, for which no sentence is quoted: colorectal cancer (2 papers); brain tumors (1); chronic hepatitis B infection (1); CNS lymphomas (1); Cognitive impairment (1); Down syndrome (1); endometrial cancer (1); Intellectual disability (1); leukemia (1); lymphoid leukemia (1); metastatic melanoma (1); oral squamous cell carcinoma (1); ovarian carcinoma (1); pancreatic cancer (1); Rett syndrome (1); testicular cancer (1); uterine cancer (1).